IL6 (interleukin 6)
Diseases named in the same sentence as IL6 in open-access papers (continued):
Sharing a sentence is not in itself a finding about the gene and the disease.
inflammation (continued). "It increases interleukin-1β (IL-1β), interleukin-6 (IL-6), interleukin-8 (IL-8), and interleukin-18 (IL-18) abundance and miR-133a expression, inhibits NF-κB, and decreases phosphorylation of the ASK1/MKK7/JNK pathway in cardiomyocytes, causing cardiac inflammation and fibrosis." (PMID 40362211, 2025). "Systemic and pulmonary inflammation was measured by enzyme-linked immunosorbent assays of plasma and bronchoalveolar lavage (BAL), respectively, which included tumor necrosis factor alpha (TNF-α), interleukin 6 (IL-6), IL-10, C-X-C motif ligand 2 (CXCL2), and CXCL5." (PMID 38928327, 2024). "Additionally, previous reports have shown that elevated circulating TMAO could induce low-grade chronic systemic inflammation through various inflammatory proteins (IL-6, ICAM1, COX2, LPS etc.)and contribute to metabolic dysfunction." (PMID 38982486, 2024). "Similarly, BLM injection significantly increased the serum level of SP-D (lung injury marker secreted by alveolar epithelial type II cells) and the wet weight of the left lung and Ccl-2/Mcp-1 and Il-6 mRNA expression in the lung, indicating the progression of lung inflammation." (PMID 36050717, 2022). "Moreover, recombinant AD was observed to stimulate the production of monocyte chemoattractant protein-1 and interleukin-6 in cultured synovial fibroblasts, which indicates the plausible role of AD in synovial inflammation and progressive bone erosion in patients with RA." (PMID 33815378, 2021). "Therefore, serum IL-6 may be a reliable and easily available laboratory parameter to distinguish CD patients with intestinal inflammation." (PMID 32470973, 2020). "β2AR/Arid5a/IL‐6 axis could be a therapeutic target against cardiac inflammation." (PMID 32302067, 2020). "Furthermore, Foxo4 only reversed the upregulation of MC5R and Leptin (P<0.05), and the downregulation of Foxo4 and IL-6 by αMSH in mRNA level (P<0.05), suggesting that αMSH may inhibit adipocyte inflammation partly via Foxo4 transcriptional regulation." (PMID 28514752, 2017). "In addition, TNF-α and IL-6 levels, indicators of lung inflammation, significantly correlated with sCD74 release (r = 0.511 and 0.585, p < 0.05), suggesting that increased sCD74 levels could partly reflect inflammation of lung injury." (PMID 27444250, 2016). "In vivo studies in Il-6-knockout mice demonstrated that the deletion of the Il-6 gene decreases lung inflammation in a model of acute lung injury and protects from mortality and the development of organ failure in a zymosan-induced acute peritoneal inflammation." (PMID 23853427, 2013). "In addition, excessive intake of cholesterol may cause vascular inflammation, and pro-inflammatory cytokines such as TNF-α and IL-6 may stimulate the expression of adhesion molecules and chemokines such as VCAM-1, ICAM-1, and fibronectin in aorta tissue." (PMID 24364887, 2013). "A systematic review of human clinical trials carried out between 1980 and 2019 revealed that curcumin supplementation increased IL-10 levels and decreased MCP-1, TNF-α, IL-6, and CRP levels, reflecting its anti-inflammatory properties in chronic inflammation." (PMID 40420174, 2025). "The pathogenesis of RA involves the infiltration of leukocytes into synovial tissue and an increase in the production of inflammatory cytokines, such as interleukin (IL)-6 and tumor necrosis factor (TNF), resulting in chronic synovial inflammation." (PMID 40565171, 2025). "Once activated, these T cells stimulate inflammatory responses by releasing pro-inflammatory cytokines such as interleukin-1 (IL-1), interleukin-6 (IL-6), and tumor necrosis factor-alpha (TNF-α), contributing to synovial inflammation and joint destruction." (PMID 40236704, 2025). "Further, visceral fat as an active secretory tissue can produce pro-inflammatory cytokines, including IL-1β, IL-6, and TNF-α, adipokines, and other biochemical modulators, which can contribute to systemic and peripheral vascular inflammation." (PMID 41010392, 2025).
inflammation (continued). "In a separate study, Glutamine decreased the levels of the inflammatory cytokines IL-1β, IL-6 and TNF-α in mice with ulcerative nodular inflammation." (PMID 39367233, 2025). "For example, γδ T cells originating in the intestine can migrate to the lungs via the bloodstream and produce cytokines such as interleukin-6 (IL-6), IL-22, TNF-α, and IFN-γ, which exacerbate pulmonary inflammation." (PMID 41357831, 2025). "This activation promotes the release of pro-inflammatory cytokines such as IL-6 and TNF-α, ultimately resulting in synovial inflammation and cartilage destruction." (PMID 40444099, 2025). "Specifically, we observed that miR-425a-5p overexpression effectively reduced pro-inflammatory cytokine production (IL-1β, IL-6, and TNF-α) in LPS-stimulated AC16 cardiomyocytes and ameliorated cardiac inflammation in the EAM mouse model." (PMID 40433545, 2025). "The secretion of IL-6, IL-1β, TNF-α and other inflammatory factors is usually significantly up-regulated in animal models of intestinal inflammation." (PMID 40746956, 2025). "Chronic inflammation, accompanied by a marked elevation of inflammatory factors such as TNF-α, IL-6, and MCP-1, disrupts the spermatogenic niche and thereby impairs sperm maturation and viability." (PMID 41198620, 2025). "Consistent with qRT‐PCR results of gene expression, enzyme‐linked immunosorbent assay (ELISA) results also showed that B‐PM treatment decreased the levels of cytokines (IL‐4, IL‐6, and IL‐17A) in BALF of mice with airway inflammation." (PMID 39950864, 2025). "Chronic inflammation in CKM is characterized by high pro-inflammatory cytokines (e.g., IL-1β, IL-6, TNF-α), which activate NF-κB signaling." (PMID 40227756, 2025). "Modern pharmacological research indicates that XBCD can downregulate inflammatory mediators, notably IL-6 and TNF-α, thereby mitigating lung inflammation." (PMID 40342990, 2025). "Circulating markers such as IL-6, myeloperoxidase (MPO), MMP-9, hsCRP, CD47, and LDL cholesterol have demonstrated utility in characterizing chronic vascular inflammation." (PMID 41007845, 2025). "Compared to HFD‐fed WT mice, HFD‐fed Nod1−/− mice exhibited increased lung inflammation, as evidenced by higher neutrophil MPO expression and activity and elevated secretion of the cytokines TNF‐α, IL‐1β, and IL‐6." (PMID 40616268, 2025). "By means of pathological staining and ELISA of periapical tissues, this paper revealed the mitigating effect of Pue on periapical inflammation, bone destruction and its suppression on the production of TNF-α, IL-1β and IL-6 in PD mice." (PMID 40312745, 2025). "Tongxinluo also reduces vascular endothelial inflammation by inhibiting inflammatory factors such as TNF-α, IL-1β, and IL-6." (PMID 40761406, 2025). "IL-33 orchestrates tissue remodeling and immune response in chronic airway inflammation through both TH2 (initiated by ILC2 matured by IL-33) and TH17 (via IL-1β and IL-6 derived from IL-33-matured DCs) immune responses." (PMID 39244793, 2024). "As expected, β-glucan treatment remarkably reduced neutrophil numbers in BALF and lung tissue, M. pneumoniae burden and LDH levels in BALF, and the levels of proinflammatory cytokines (IL-1β, IL-6, and TNF-α), which led to the remission of lung inflammation." (PMID 39499730, 2024). "Chronic systemic inflammation, through the activation of immune cells such as macrophages and T cells, leads to the production of inflammatory cytokines (TNF-α, IL-1, and IL-6) that directly influence bone metabolism." (PMID 38841589, 2024). "After the induction of nasal mucosal inflammation, the changes in IgE, IL-17, TNF-α, and IL-6 concentrations in the model group indicated upregulation of these markers and suggested successful induction of inflammation." (PMID 38369554, 2024).
inflammation (continued). "Several reports suggest that IL-10 can inhibit antigen presentation and downregulate the formation and secretion of IL-1, IL-6, TNF-α, and other critical inflammatory aspects in macrophages and T cells, thus improving IBD intestinal inflammation." (PMID 38891089, 2024). "The occurrence of low-grade chronic inflammation in individuals with T2DM triggered an excessive secretion of inflammatory markers, including CRP, interleukin-6 (IL-6), TNF-α and monocyte chemokine 1(MCP-1)." (PMID 38528483, 2024). "It has been found that DEP induced lung inflammation in mice, which displayed increased macrophages in BALF, an increase in the expression of IL-6, TNF-α, and NF-κB in pneumocytes, and a corresponding increase in the collagen fiber content of alveolar septa." (PMID 39324058, 2024). "Moreover, alirocumab not only affects lipid levels but may also offer additional cardiovascular benefits by reducing the activity of inflammatory cytokines (such as IL-18, IL-6, TNF-α) and other molecules associated with vascular inflammation (such as MMP-2, OPN, OPG)." (PMID 38017531, 2023). "BLM induces pulmonary inflammation and PF within a short time, while BLM administered intratracheally up-regulates fibrotic factor levels, like IL-1β, IL-6, TNF-α, and TGF-β, etc.." (PMID 37160579, 2023). "Proinflammatory cytokines such as IL-6, TNF-α, and MCP1 are key in the pathogenesis of intestinal inflammation." (PMID 36968461, 2023). "Chronic inflammation, often referred to as inflammaging, is characterized by increased levels of pro-inflammatory markers such as IL-1, TNF, IFN, and IL-6 in geriatric patients." (PMID 37893234, 2023). "In the GFAP-IL6 transgenic mouse, IL6 is overexpressed in the brain under the control of the GFAP promoter, as a model of chronic brain inflammation." (PMID 35978857, 2022). "Previous studies have shown that PM2.5 can induce the release of various pro‐inflammatory cytokines, including TNF‐α, granulocyte‐macrophage colony‐stimulating factor (GM‐CSF), and IL‐6, from HBE cells and macrophages, leading to airway inflammation." (PMID 35312179, 2022). "In this study, LF-N2 significantly inhibited IL-6, increased the levels of IL-4 and IL-10 in serum, and the gene expression of NOS in gastric tissue, thereby inhibiting gastric inflammation and injury." (PMID 35299759, 2022). "Our study showed that IL-10 treatment significantly decreased TNF-α infiltration and the expression of IL-1β, IL-6, IL-8, and TNF-α in Ang II-induced vascular inflammation." (PMID 35528508, 2022). "Chronic intestinal inflammation is closely related to the expression of pro-inflammatory factors such as TNF-α, IL-1β, IL-6 and IL-8." (PMID 36185671, 2022). "In summary, these findings demonstrate the efficacy of combined pharmacological inhibition of IL-6 and TNF in suppression of Th17-mediated airway inflammation." (PMID 35408882, 2022). "In the rat model, TQ was found to decrease interleukin-1β (IL-1β), IL-6, IFN-β, TNF-α and prostaglandin (PGE), which prevent pulmonary inflammation." (PMID 36558399, 2022). "Lycopene alleviated HDF-induced renal inflammation by inhibiting the TLR4/MyD88 inflammatory pathway by blocking inflammation in mice kidneys, including NF-kB, TNF-a, and IL-6." (PMID 36230117, 2022). "Our results showed that exosomes and miR-150 partially attenuated lung inflammation, including total cells, neutrophils, macrophages, TNF-α, IL-6, and IL-1β." (PMID 34750610, 2022). "Persistent liver inflammation, immune-mediated liver damage, and upregulation release of proinflammatory cytokines TNF-α and IL-6 are present in NASH, chronic HBV, and HCV-induced HCC." (PMID 36189208, 2022). "During pulmonary inflammation, macrophages differentiate into M1 type and release pro-inflammatory factors (TNF-α, IL-6 and MCP-1)." (PMID 35266443, 2022).
inflammation (continued). "Under such conditions, monocytes, macrophages, IL-6, IL-1β, and TNF-α, which are involved in increasing oxidative stress and peripheral vascular inflammation, are likely to enhance subsequent progression of inflammation." (PMID 35370896, 2022). "Clearly, GMP showed capacity in fighting OxS in the circulation (MDA and F2 isoprostanes) and liver (GPx1), and in alleviating liver inflammation, which is documented by a decline in inflammatory biomarkers (COX-2, TNF-α and IL-6)." (PMID 34572325, 2021). "We already confirmed that intraperitoneal injection of TNF-α induced vascular inflammation, such as macrophage infiltration and abnormal mRNA expression of VCAM-1 and inflammatory cytokines such as IL-6 and TNF-α in the mouse aorta." (PMID 34679642, 2021). "It is well known that the NF-κB pathway is crucial for the production of inflammatory cytokines, including IL-6 and TNF-α, both of which are important targets for the treatment of intestinal inflammation." (PMID 34322027, 2021). "Improve lung inflammation by inhibiting the excessive recruitment of M1 and M2 under TGF-β1 to achieve a therapeutic effect, reducing the levels of MCP-1, TNF-α, IL-1β, IL-6, IL-10,IL-13, and OSM." (PMID 34489700, 2021). "In asthmatic subjects with neutrophilic airway inflammation, potential targets of ICS include the cytokine interleukin-6 (IL-6) and the neutrophil-attracting chemokine CXCL1." (PMID 34871316, 2021). "Previous research has shown that IL-6, IL-1β, MCP-1, NF-κB, TNF-α, ICAM-1 and VCAM-1 are all involved in the process of vascular inflammation." (PMID 34830730, 2021). "The gene expression of IL-1β, IL-6, and TNF-α in rat models of acute joint inflammation and in the cartilage of rat models of OA decreased significantly after LLLT (808 nm, 142 J/cm2) and laser irradiation (808 nm, 71 J/cm2), respectively." (PMID 32213810, 2020). "The increased production of proinflammatory cytokines and chemokines, including TNF-α, IL-6, IL-8 and MCP-1, during H. pylori gastric mucosal inflammation, has been well documented." (PMID 32230910, 2020). "The results of Elisa (IL-6, MCP-1, TNF-α, and IL-1β) in the BALF and HE in the lungs of mice showed that Tre alleviated CS-induced pulmonary inflammation." (PMID 31947943, 2020). "Activated lung macrophages have also been shown to enhance IL6 trans-signaling via ADAM-17 leading to fibroblast proliferation and ECM deposition, and inhibition of sIL6Rα can attenuate pulmonary inflammation and fibrosis." (PMID 32210969, 2020). "Consumption of a low-fiber, high-fat, Western-style diet induces adiposity and adipose inflammation characterized by elevations in the M1:M2 macrophage ratio and pro-inflammatory TNF-α and IL-6 expression." (PMID 32092918, 2020). "In order to evaluate the effect of antibiotic treatment on PA-induced lung inflammation, we assessed the ICAM and IL-6 mRNA expression in the lung tissue in WT mice." (PMID 31488203, 2019). "We found that after unilateral DMV damage, the protective function of the vagus efferent nerve by Ach attenuated, esophageal inflammation aggravated, and the concentrations of the proinflammatory cytokines TNF-α, IL-6, and IL-1β significantly increased." (PMID 31281769, 2019). "Pro-inflammatory cytokines such as IL-1α, IL-1β, IL-2, IL-5, IL-6, IFN-γ, MCP-1, MIP-1α, MIP-1β and TNF-α are shown to play an essential role in inducing age-related chronic inflammation." (PMID 31181695, 2019). "Particularly, chronic systemic inflammation in HD patients as indicated by increased levels of inflammatory markers such as C-reactive protein (CRP) and interleukin-6 (IL-6) are strong predictors for CVD and overall mortality." (PMID 29570616, 2018). "The GPR55 inhibitor CID16020046 reduced TNF-α, IL-1β, IL-6, and COX-2 levels in a mouse model of intestinal inflammation." (PMID 30453998, 2018).
inflammation (continued). "There is a body of evidence supporting GM-CSF as an important mediator in lung inflammation by upregulating TLR2, TLR4, and CD14 expression, and by boosting IL-6 and IL-1β production from macrophages." (PMID 30013577, 2018). "The intestinal inflammation is characterized by a Th1 and Th17-mediated responses with enhanced expression of TNF-α, IFN-γ, IL-1β, IL-12, IL-6, IL-10 and IL-1761." (PMID 29872077, 2018). "To demonstrate the effect of curcumin on mice BAL fluids, we detected the secretion of the pro‐inflammatory cytokines TNF‐α, IFN‐α, and IL‐6, which contribute to IAV‐induced lung inflammation." (PMID 28646616, 2017). "Chronic inflammation is known to play a major role in the pathological mechanism of COPD, and inflammatory cytokines, such as MCP-1, IL-2, IL-6, and IL-10, are known to promote inflammation." (PMID 29234369, 2017). "In addition, KC and IL-6 may be key inflammatory mediators for the increase in airway inflammation." (PMID 27294946, 2016). "In vitro, co-culture of differentiated 3T3-L1 adipocytes and RAW264 macrophages is used as the model of adipose inflammation in which pro-inflammatory cytokine genes and proteins such as CCL2, IL-6 and TNF-α are significantly upregulated." (PMID 26901838, 2016). "Macrophage infiltration into WAT, which is accompanied by IL-6 and TNF-α production, is an early contributing event for the development of chronic low-grade systemic inflammation." (PMID 26871288, 2016). "After 6 h of MV, interleukin (IL)-6 and IL-8 levels were elevated in bronchoalveolar lavage (BAL) fluid and plasma in patients who received higher VT/low PEEP, suggesting alveolar lung inflammation." (PMID 27303668, 2016). "Intestinal inflammation in colitic controls was characterized by a marked increase in pro- and anti-inflammatory cytokines TNF-α, IFN-γ, IL-1β, IL-6, IL-12, and IL-10, compared to normal controls." (PMID 27293323, 2016). "Consistent with worsened renal dysfunction, Ang II infusion in the ApoEKO mice exhibited exacerbation of kidney inflammation with enhanced expression of TNF-α, TNFRSF1A, IL-1β, IL-6, and IL-17A." (PMID 26245758, 2015). "On the other hand, chronic inflammation is known to be enhanced with healthy aging, and we found that inflammatory factors such as CRP, adiponectin, TNF-α, and IL-6 were elevated in SSCs." (PMID 26559536, 2015). "IL-6, IL-1β, and TNF-α are all important cytokines that stimulate RASFs and inflammatory cells to aggravate synovial inflammation, resulting in joint destruction." (PMID 26303122, 2015). "Inflammatory factors such as ICAM-1, VCAM-1, TNFα, IL-6, and CRP have key roles in mediating vascular inflammation and blocking RAAS negatively modulates the levels of these inflammatory molecules." (PMID 24804145, 2014). "Acute pulmonary inflammation was assessed by histology, pulmonary myeloperoxidase (MPO) activity, and pulmonary IL-6 concentration." (PMID 24886543, 2014). "Cows with persistent uterine inflammation had higher serum concentrations of adiponectin, TNF-α, IL-1β and IL-6 compared to normal and recovered cows." (PMID 24209779, 2013). "In a model of organic dust-induced airway inflammation, TLR2 knockout mice had significantly lower airway neutrophils, IL-6, TNF-α, and CXCL-1 (mouse homolog of CXCL8) compared with wild-type controls suggesting that airway inflammation is dependent on TLR2." (PMID 23606791, 2013). "Dexmedetomidine (10and 20 μg/kg) significantly decreased mortality and pulmonary inflammation of septic rats, as well as suppressed CLP-induced elevation ofTNF-α and IL-6 and inhibited TLR4/MyD88 expression and NF-κB activation." (PMID 23690665, 2013). "Cows with persistent postpartum uterine inflammation had higher serum concentrations of TNF-α, IL-6, leptin, but lower insulin and IGF-1 compared to normal and spontaneously recovered cows and there was a temporal association observed during the study period." (PMID 24209779, 2013).